HDAC5 (histone deacetylase 5)
Diseases named in the same sentence as HDAC5 in open-access papers (continued):
Sharing a sentence is not in itself a finding about the gene and the disease.
melanoma (9 papers, 2016 to 2025). A malignant, usually aggressive tumor composed of atypical, neoplastic melanocytes. "Over-expression of HDAC5 in melanoma, and in other malignancies, is associated with enhanced growth and a shorter patient survival." (PMID 33898322, 2021). "Other authors demonstrated that knocking down HDAC5 or HDAC6 inhibited melanoma cell proliferation and promoted apoptosis." (PMID 38542774, 2024). "This study was designed to investigate effect of the HDAC3/miR‐495‐3p/TRAF5 axis in the development of melanoma, and we found that the inhibition of HDAC5 has the ability to elevate miR‐495‐3p to restrain the progression of melanoma by reducing TRAF5." (PMID 33048450, 2020). "Here, we showed the expression levels of all 11 HDACs in multiple melanoma cells comparing with normal skin cells and found that HDAC5 and HDAC6 have lower expression levels in normal tissues but much higher expression in A375 and A2058 cells." (PMID 26747087, 2016). "To clarify the roles of HDAC5 and HDAC6 in melanoma progression, we designed three shRNA sequences for knocking down HDAC5 or HDAC6." (PMID 26747087, 2016). "We used CCK8 to identify cell proliferation after reducing HDAC5 or HDAC6 expression levels in melanoma cells." (PMID 26747087, 2016). "This study provided evidence for the first time that melanoma specifically overexpressed HDAC5 and HDAC6." (PMID 26747087, 2016). "We believe that both HDAC5 and HDAC6 could be good diagnostic and therapeutic targets for controlling melanoma." (PMID 26747087, 2016). "Similarly, silencing of HDAC5 inhibited tumour growth in melanoma mouse xenograft models." (PMID 38369747, 2024). "MC1568 decreases the levels of interleukin-8 and the proliferation of melanoma cells, and has shown potent and specific inhibition of class II HDACs, such as HDAC4 and HDAC5." (PMID 34203519, 2021). "When tested for expression levels, both HDAC5 and HDAC6 had higher protein levels in melanoma cells (M257, SK-MEL-28, A375 and A2058 cells) than normal skin cells (HaCaT)." (PMID 26747087, 2016). "In this present study, we showed that knockdown of HDAC5 or HDAC6 prevented proliferation and induced apoptosis of the melanoma cells." (PMID 26747087, 2016). "In most samples, the levels of total HDAC5 and HDAC6 were higher in melanoma tissues than normal skin tissues." (PMID 26747087, 2016). "In this study, and found that HDAC5 and HDAC6 were highly expressed in melanoma cells but exhibited low expression levels in normal skin cells." (PMID 26747087, 2016). "We presented both HDAC5 and HDAC6 as tumor promoters in melanoma proliferation and metastasis through different signaling pathway, and shaded some light on the potential mechanisms." (PMID 26747087, 2016). "This study demonstrated both HDAC5 and HDAC6 were required for melanoma cell proliferation and metastasis through different signaling pathways." (PMID 26747087, 2016). "We used overexpression and knocking down lentivirus to clarify the influence of HDAC5 and HDAC6 in melanoma development." (PMID 26747087, 2016). "Independent from vemurafenib resistance, the curcumin-harmine-isovanillin combination drug GZ17-6.02 upregulated class I MHCA and suppressed PD-L1 in PDX BRAFV600E melanoma cells, which was mediated by the downregulation of several HDACs (HDAC3, HDAC5, HDAC6, HDAC7, and HDAC8)." (PMID 39935431, 2025). "Knockdown of HDAC5 or HDAC6 can cause apoptosis and cell cycle arrest, meanwhile, suggesting that there is no functional redundancy in A375 melanoma cells between HDAC5 and HDAC6." (PMID 26747087, 2016). "For clarifying the sublocations of HDAC5 and HDAC6 in melanoma tissues, we then performed immunohistochemistry in 10 clinical melanoma samples, including 46 samples that had the adjacent normal melanoma tissues." (PMID 26747087, 2016). "Finally, we tested HDAC5 and HDAC6 expression and sub-location in clinical melanoma tissues and tumor adjacent tissues." (PMID 26747087, 2016).
melanoma (continued). "Furthermore, we knocked down HDAC5 or HDAC6 in A375 cells and demonstrated that both HDAC5 and HDAC6 contributed to the proliferation and metastasis of melanoma cells." (PMID 26747087, 2016). "Interestingly, HDAC5 and HDAC6 may influence melanoma cell proliferation through different pathways." (PMID 26747087, 2016). "However, western blots did not demonstrate the specific location of HDAC5 or HDAC6 in melanoma tissues." (PMID 26747087, 2016). "Thus, we suggest that HDAC5 and HDAC6 may contribute to the occurrence of melanoma." (PMID 26747087, 2016).
colorectal cancer (8 papers, 2006 to 2024). A primary or metastatic malignant neoplasm that affects the colon or rectum. "HDAC5 also increased DLL4 expression in colorectal cancer (CRC) cells, thereby enhancing their proliferation." (PMID 34178647, 2021). "HDAC1, HDAC5, HDAC7A, SIRT1, and SUV39H1 expression profiles were distinctive for colorectal cancers and normal colorectal mucosa." (PMID 16638127, 2006).
diabetes (8 papers, 2020 to 2025). "Furthermore, HDAC5 is involved as a common pathogenic factor in both type 1 and type 2 in vivo animal models of diabetes." (PMID 36360783, 2022). "In the kidneys of diabetes people and animals, the levels of histone deacetylase 5 (HDAC5), a member of the class II HDAC subfamily, are greater than average." (PMID 37841018, 2023). "To further elucidate the function of HDAC5 in renal tubular cells of diabetes mellitus, we knocked down HDAC5 in HK2 cells treated with high glucose using shRNA plasmid targeted at HDAC5 (pGenesil-1-HDAC5)." (PMID 33414476, 2021). "We hypothesized the AMPK-HDAC5 regulatory pathway, previously studied in diabetes and cardiovascular disease, may be involved with the reduction of HDAC5 levels in WD mice, since activated AMPK signaling has been reported in animal models of copper accumulation." (PMID 34098115, 2021). "Considering that PI3K/Akt pathway is the pivotal pathway to regulate renal tubular cell function in diabetes mellitus, we further explored the potential influence of PI3K/Akt pathway on high glucose-induced HDAC5 upregulation in HK2 cells." (PMID 33414476, 2021). "Acetate not only improved the hypothalamic-pituitary-ovarian function of female patients with T2DM by inhibiting histone deacetylase-5 (HDAC5), but also alleviated the testicular dysfunction in male patients with diabetes by inhibiting proprotein convertase subtilisin/kexin type 9 (PCSK9)." (PMID 35242721, 2022). "HDAC5 inhibitors are a novel treatment for diabetes mellitus that increases GLUT4 gene expression, suggesting that metrnl might also treat diabetes by increasing GLUT4 expression." (PMID 32196931, 2020).
gastric cancer (8 papers, 2018 to 2024). A primary or metastatic malignant neoplasm involving the stomach. "Expression profiling of histone-modifying genes during gastric cancer progression revealed decreased expression of HDAC5 during gastric cancer progression." (PMID 39497715, 2024). "In contrast, although HDAC5 was shown to induce tissue invasion of gastric cancer cells, gene expression profiles of histone modifiers indicate that HDAC5 is downregulated in gastric cancer." (PMID 34178647, 2021). "In addition, HDAC5 enhanced the invasiveness of gastric cancer cell lines by stimulating protein kinase C (PKC)/matrix metalloproteinase 9 (MMP9)." (PMID 34178647, 2021). "A previous study showed that HDAC5 was induced in gastric cancer cells." (PMID 30286788, 2018). "Here, we also provide evidence for high expression of HDAC5 in gastric cancer, and knockdown of HDAC5 inhibits the proliferation of GC cells." (PMID 30286788, 2018). "For example, the regulatory effect ofHOXC-AS3 on HDAC5 expression is mediated through its interaction with YBX1, which facilitates the proliferation and migration of gastric cancer cells." (PMID 38899362, 2024). "Univariate Cox regression analysis revealed that HDAC1, HDAC5, HDAC8, SIRT3, and SIRT6 were significant predictors of gastric cancer." (PMID 37649598, 2023). "Our results showed that HOXC-AS3 could bind to YBX1, thus transcriptionally regulating a large set of genes that are linked to cell proliferation and cell migration in gastric cancer cells, such as MMP7, WNT10B, and HDAC5, thus promoting GC cell proliferation and migration." (PMID 30286788, 2018).
lung adenocarcinoma (8 papers, 2019 to 2026). A carcinoma that arises from the lung and is characterized by the presence of malignant glandular epithelial cells. "For instance, in lung adenocarcinoma, HDAC5-mediated deacetylation of SATB1 can also affect its transcriptional regulatory activity on downstream genes." (PMID 40781327, 2025). "The ceRNA mechanism, involving genes like TENM4, XRCC2, HDAC5, CDKN1A, ARFGEF3, SNAP25-AS1, RP11-58O9.2, LINC01164, VLDLR-AS1, and RP11-14I17.2, may play a role in lung adenocarcinoma (LUAD) development linked to tumor hypoxia." (PMID 39236027, 2024). "Similarly, the upregulation of HDAC5 has been found to promote lung adenocarcinoma by regulating several cell cycle and epithelial-mesenchymal transition genes, and in our analysis, CollecTRI regulons predicted its increased activity in LUAD." (PMID 37843125, 2023).
Cerebral ischemia (6 papers, 2015 to 2022). Restriction of arterial blood supply to the brain associated with insufficient oxygenation to support the metabolic requirements of the tissue. "In one study, miR-217 promotes the accumulation of HDAC5 in the nucleus and affects the cerebral ischemia-reperfusion injury via the miR-217/MEF2D/HDAC5 axis." (PMID 32963637, 2020). "In addition, in vitro experiments showed that miR-217 promotes the accumulation of histone deacetylase 5 (HDAC5) in the nucleus by targeting MEF2D, resulting in decreased expression of IL-10, thereby aggravating cognitive dysfunction after cerebral ischemia." (PMID 36399471, 2022). "HDAC5 and HDAC4 were markedly reduced in both cerebral ischemia/reperfusion injury and OGD model, and NADPH oxidase-reduced HDAC4 and HDAC5 accelerates cerebral ischemia injury via increasing the expression and release of high mobility group box-1 protein (HMGB1)." (PMID 27330844, 2016).
neuroblastoma (6 papers, 2016 to 2024). Neuroblastoma (NB) is the most common solid, extracranial childhood tumor. "HDAC5, a member of the class IIa HDAC family, has previously been implicated in promoting the invasion and metastasis of neuroblastoma." (PMID 33117806, 2020). "Here we identified GRHL1 as a transcriptional activator of the CD9 gene and showed that MYCN and HDAC5 transcriptionally repress CD9 in neuroblastoma." (PMID 27572323, 2016). "Taken together, CD9 is epigenetically and transcriptionally repressed by the chromatin-modifying enzyme, HDAC5, in association with MYCN, and CD9 expression can be triggered in neuroblastoma cells by inhibition of HDAC5." (PMID 27572323, 2016). "HDAC5 also promotes neuroblastoma cell proliferation and has been targeting using siRNA, yielding a decrease in proliferation." (PMID 26771642, 2016). "Our data argue a role for HDAC5 in transcriptionally repressing CD9 in neuroblastoma cells beyond the repression achieved by MYCN and DNA methyltransferases, and offers an avenue for pharmacological intervention." (PMID 27572323, 2016). "HDAC5 was also observed to block N-myc-mediated differentiation in neuroblastoma cells." (PMID 34178647, 2021). "In neuroblastoma, HDAC5 promoted cell proliferation but had little effect on cell death." (PMID 34178647, 2021). "Although CD9 expression could be elevated by either HDAC5 siRNA, or treatment with the HDACi panobinostat, across a number of neuroblastoma cell lines, siRNA mediated knockdown of HDACs 2, 3, and 10 elicited opposing effects on CD9 expression." (PMID 33117806, 2020). "Additionally, HDAC5 has also been shown to block neuroblastoma cell differentiation and induce proliferation through an interaction with N-Myc." (PMID 33117806, 2020). "Interestingly, HDAC5 was also shown to interact with N-myc protooncogene protein (MYCN), and the complex colocalized to the CD9 promoter and attenuated CD9 expression in neuroblastoma cells, leading to tumor cell invasion and metastasis." (PMID 34178647, 2021). "However, no small molecule inhibitor specific for HDAC5 has been used in neuroblastoma." (PMID 26771642, 2016).
breast tumor (5 papers, 2006 to 2022). "The present study shows that HDAC5 mRNA and protein were both widely expressed in breast tumor tissues and that the relatively high expression of HDAC5 was associated with an inferior prognosis in patients with BC." (PMID 27177225, 2016). "We aimed to evaluate HDAC5 expression in human breast tumors and to determine the effects of the inhibition of HDAC5 expression in BC cells." (PMID 27177225, 2016). "In addition, we performed immunohistochemistry (IHC) to evaluate HDAC5 protein expression on tissue microarrays (TMA) containing 450 breast tumor samples." (PMID 27177225, 2016). "Breast cell lines showed downregulation of HDAC1, HDAC2, HDAC5, EZH2, EP300, and PCAF compared to breast tumours." (PMID 16638127, 2006).
cocaine addiction (5 papers, 2019 to 2022). "Long-term alcohol consumption promotes the degradation of HDAC5 and may increase vulnerability to cocaine addiction (Griffin Jr." (PMID 36389068, 2022). "Importantly, Nester and colleagues have shown that loss of HDAC5 in NAc sensitizes neuronal responses to chronic, but not acute, cocaine administration, suggesting that HDAC5 in the reward system is a key regulator in the transition to cocaine dependence." (PMID 36540409, 2022). "HDAC5 controls the negative regulation of BDNF expression, which is upregulated in cocaine addiction." (PMID 34638996, 2021).
colon cancer (5 papers, 2013 to 2025). "Ouyang and colleagues discovered that miR-148a-3p inhibited the mobility of colon cancer cells by zeroing in on HDAC5." (PMID 41114868, 2025).
cyst (5 papers, 2015 to 2023). A sac-like closed membranous structure that may be empty or contain fluid or amorphous material. "In Pkd2-deficient mice, the reduction of HDAC5 inhibits cyst formation by enhancing MEF2C-dependent transcription." (PMID 37878054, 2023). "Genetic inhibition of HDAC5, even heterozygosity, can suppress cyst formation caused by the Pkd1 mutation, providing the genetic basis supporting HDAC5 as a therapeutic target for ADPKD disease intervention." (PMID 31059522, 2019). "In this study, we first show genetic inactivation of Hdac5 can suppress cyst formation in Pkd1–/–mice." (PMID 31059522, 2019). "We further investigated the mechanism by which dopamine receptor antagonists promotes HDAC5 nuclear export and demonstrated the ability of one of these compounds to slow cyst growth in Pkd1–/–mice." (PMID 31059522, 2019). "Stimulation of polarized epithelial monolayers with fluid flow induced phosphorylation and nuclear export of HDAC5 whereas dwonregulation of HDAC5 or treatment with TSA reduced cyst formation in Pkd2−/− mouse embryos." (PMID 25972812, 2015). "Bromocriptine, amisulpride, and mirtazapine were all shown to target Drd3 specifically, and therefore may be particularly effective in cyst reduction and cell proliferation by HDAC5 nuclear export." (PMID 37217845, 2023). "In this work, we first wanted to test whether genetic inhibition of Hdac5 could also reduce cyst formation in Pkd1–/–mice after birth." (PMID 31059522, 2019). "Combining the findings that genetic inhibition of HDAC5 can suppress cyst formation and dopamine antagonists promotes robust HDAC5 nuclear export, we hypothesized that the dopamine antagonist can impede cyst development in ADPKD mice." (PMID 31059522, 2019). "This led us to hypothesize that the renal HDAC5 regulation in response to increased fluid stress may also play a role in strengthening epithelial function and architecture and, thus, preventing renal injury and cyst development." (PMID 31059522, 2019). "The results described in this study in combination with previous work demonstrate that HDAC5, a class IIa HDAC, is a target of polycystin-mediated fluid sheer stress sensation and plays a role in cyst formation and the development of ADPKD." (PMID 31059522, 2019). "Determining when this is the appropriate action is an area of future research.HDAC5 upregulates MEF2C; in turn, MEF2C is known to be missing during metastasis, the latter of which is necessary for ciliogenesis; conversely, inhibition of HDAC5 suppresses cyst formation that disrupts cilia formation." (PMID 35859153, 2022).
osteosarcoma (5 papers, 2016 to 2025). A usually aggressive malignant bone-forming mesenchymal neoplasm, predominantly affecting adolescents and young adults. "One example is upregulation of the histone deacetylase HDAC5 in osteosarcoma, which via its gene repressive function, activates downstream TWIST1 expression, a known oncogene and EMT driver." (PMID 40442778, 2025). "HDAC5 induced osteosarcoma cell proliferation in a Twist1-dependent manner, highlighting the varied functions of the HDAC5/Twist1 axis in tumor progression." (PMID 34178647, 2021). "HDAC5 preferentially localized at long telomeres and maintains their length, and HDAC5 silencing was found to increase the sensitivity of osteosarcoma and fibrosarcoma cells with long telomeres to chemotherapy." (PMID 34178647, 2021). "Twist1 is a downstream target of HDAC5 in osteosarcoma progression." (PMID 34178647, 2021). "In addition, the expression levels of several other HDAC family members, such as HDAC2, HDAC3, HDAC5, and HDAC8 were also upregulated, suggesting a potentially redundant function of HDACs in osteosarcoma." (PMID 37457661, 2023). "The TWIST1 negative regulator, deactivated by HDAC5, was not reported, though independently, miR-22 is a known direct regulator of TWIST1 where low miR-22 levels in osteosarcoma tumours contributes to EMT and disease progression through TWIST1." (PMID 40442778, 2025).
renal fibrosis (5 papers, 2016 to 2025). A final common manifestation of a wide variety of chronic kidney diseases characterized by glomerulosclerosis and tubulointerstitial fibrosis. "Interestingly, in unilateral ureteral obstruction (UUO) mice known as the classical renal fibrosis model, we found the prominently increased expression of HDAC5 in renal tubular cells located in fibrotic interstitium region, in comparison with those cells located in normal region." (PMID 33414476, 2021). "Moreover, HDAC5 and HDAC4 were both upregulated in a model of renal fibrosis and suggested to contribute to its pathogenesis." (PMID 31052182, 2019). "Piceatannol may be a beneficial therapeutic agent for treating renal fibrosis via reduction of HDAC4 and HDAC5 protein expression or suppression of the p38-MAPK signaling pathway." (PMID 27902771, 2016). "However, the specific roles and mechanisms of HDAC5, 7, and 9 in animal models of renal fibrosis remain elusive due to the absence of dedicated class IIa inhibitors." (PMID 38929505, 2024). "Piceatannol may attenuate renal fibrosis by inhibiting HDAC4 and HDAC5." (PMID 38929505, 2024). "As so far, there was no report on the direct relationship between HDAC5 and TGF-β1, whereas HDACs inhibitors (HDACi) or other HDACs members were proven to affect TGF-β1 expression in fibrosis models including renal fibrosis." (PMID 33414476, 2021).